BCOR (BCL6 corepressor)
Diseases named in the same sentence as BCOR in open-access papers (continued):
Sharing a sentence is not in itself a finding about the gene and the disease.
tumor (continued). "CNS tumors with EP300::BCOR fusion seem to be distinct from their BCOR ITD counterparts in terms of age, location, progression-free survival, tumor growth pattern, and immunopositivity for the BCOR protein." (PMID 36782314, 2023). "Pathology review of the nasal biopsy at our center showed a tumor composed of proliferation of atypical monotonous small round cells that were focally positive for CD99 and diffusely positive for BCOR, SATB2, and TLE-1 immunostains." (PMID 38170001, 2023). "Recently, various new fusion partners of BCOR have been documented, such as MAML3, ZC3H7B, RGAG1, and KMT2D, further increasing the complexity of such tumor entities, although the molecular pathogenetic mechanism remains to be elucidated." (PMID 36765856, 2023). "Our case is unique compared to previous reports, as it represents the first report of complete pathologic tumor necrosis documented in the literature, suggesting the clinical effectiveness of the VDC-IE protocol for BCOR-rearranged round cell sarcomas." (PMID 38170001, 2023). "The tumor cells of HGESS were often smaller with irregular or tongue-like invasion into the myometrium, and CCND1 and BCOR were often positive on IHC." (PMID 36994196, 2023). "In the latest updated WHO CNS5 classification these two tumour types were incorporated as CNS neuroblastoma, FOXR2-activated and CNS tumour with BCOR internal tandem duplication (CNS BCOR ITD)." (PMID 36895035, 2023). "This study is the first to examine the SCNA status of both AH and tumor samples while simultaneously analyzing RB1, BCOR, CREBBP, and MYCN for SNV disease drivers." (PMID 37239954, 2023). "In six cases, the following matches were highlighted: one iHGG, two IDH wild-type, one BCOR internal tandem duplication (BCOR-ITD), one plexus tumor, and one MN1-rearrangement." (PMID 35204463, 2022). "Intriguingly, these tumor-specific gene fusion events contain one TF of SSX2 and seven oncogenes of SS18, SSX1, SSX2, BCOR, CNOT1, HIST2H2AC, and TOP1." (PMID 36118864, 2022). "This means that the percentage of positive cells is below the cutoff of 15% (10–12% for EWSR1) or that 0% positive tumor cells were detected (for FUS, CIC, and BCOR)." (PMID 36232302, 2022). "Samples of P07-aRMS were obtained at the same timepoint but showed different events: the primary tumour exhibited an ATRX-deletion, whilst the metastasis harboured SNVs in ATR and RAF1, a biallelic BCOR-deletion, and a MYCN-amplification." (PMID 36182817, 2022). "In particular, this revaluation confirmed the one iHGG, one with NTRK-fusion, one BCOR-ITD, and the MN1-rearranged neoplasm already identified." (PMID 35204463, 2022). "The identification so far of four chimeric transcripts in HG‐ESS—YWHAE/NUTM2A/B, ZC3H7B/BCOR, EPC1/SUZ12, and EPC1/BCOR‐is evidence of genetic heterogeneity also within this tumor subgroup." (PMID 33099834, 2021). "The IHC staining was positive for CD99 and FLI-1 (in >50% of tumor cells) and negative for AE1/AE3, INI-1 loss, WT1, desmin, myogenin, BCOR, TLE-1, CD45CLA, and synaptophysin." (PMID 41230381, 2026). "Immunohistochemically, the tumor cells were positive for GFAP and S‐100 protein, weakly positive for SOX2, focally positive for synaptophysin, and negative for TTF‐1, neurofilament protein, NeuN, EMA, chromogranin, and BCOR." (PMID 39492623, 2025). "An immunohistochemical analysis of the tumor biopsy specimen was positive for BCOR, but no BCOR gene aberrations were detected." (PMID 40799881, 2025). "Only in one tumor we found an additional pathogenic variant with our NGS panel, which was a truncating BCOR mutation (R1472 frameshift-deletion; VAF of 80%) in a PB-RB1 tumor with a homozygous RB1 deletion (not shown)." (PMID 41291966, 2025). "Moreover, the tumor was partly positive for S-100P, CD56, CD68 and LCA, while negative for chromogranin A, synaptophysin, Myo D1, CD34, calretinin and BCOR." (PMID 39930783, 2025).
tumor (continued). "In general, fusion-driven neoplasms, including JAZF1-rearranged LG-ESS, YWHAE- or BCOR-altered HG-ESS, ALK- or NTRK-rearranged IMTs, and TFE3-rearranged PEComas, harbor early, lineage-defining genomic events that are consistently detectable across disease stages." (PMID 41463261, 2025). "Of note, as for BCOR, variants in GFI1 and GSE1 were also found in single tumor samples with mutations in miRNA-processing genes (not shown)." (PMID 41291966, 2025). "A CNS tumor with BCOR/BCOR(L1) fusion is a rare tumor entity, not yet defined in the 2021 WHO classification of CNS tumors." (PMID 40724977, 2025). "The aim of this study was to investigate the possibility of a differential molecular signature between metastatic and localized BCOR-ITD-positive CCSKs at the diagnosis, which could aid in the identification of more aggressive tumor entities." (PMID 36835166, 2023). "Although recently, BCOR internal tandem duplication (ITD) has been found as a driver mutation in more than 80% of cases, a deep molecular characterization of this tumor is still lacking, as well as its correlation with the clinical course." (PMID 36835166, 2023). "Although more work is needed to understand the impact of these genes in RB pathogenesis, both BCOR and CREBBP are thought to be tumor suppressors; thus, their inactivation may contribute to disease severity." (PMID 37239954, 2023). "Her tumor molecular profile performed 2.5 years after completion of treatment with BBI608 demonstrated MYB proto-oncogene (MYB) chromosomal rearrangement, BCL6 corepressor (BCOR) P698fs, and lysine demethylase 6A (KDM6A) R1415 *." (PMID 35267638, 2022). "In addition, the immunohistochemical results showed the altered staining patterns of BCOR, bcl2, CyclinD1, TLE1, AR, SMA, CD117, STAB2, CD56, and CD99 in tumor tissues after chemotherapy." (PMID 35568949, 2022). "Collectively, our results allowed the decipherment of a functional axis whereby KPNA2 assisted the nuclear import of CBX8 to activate downstream effectors by recruiting BCOR to the promoter region of PRDM1, thus highlighting the tumor-promoting properties of KPNA2 in BCa." (PMID 33731128, 2021). "Two tumors with negative result showed diffuse and strong BCOR nuclear immunopositivity, including tumor with unique papillary architecture originally diagnosed as unclassified malignant neuroepithelial tumor." (PMID 32650833, 2020). "VAFs of BCOR and CREBBP were well below 1, indicating that not all alleles were mutated and therefore possibly not all tumor cells harbored these secondary variants." (PMID 27126562, 2016). "Similarly, VAFs of BCOR and CREBBP and amplitudes of most of the large SCNAs were consistent with intra-tumor heterogeneity." (PMID 27126562, 2016). "Importantly, in addition to the aberrant reactivation of genes on the inactive X, aberrant silencing of several genes that normally escape XCI, such as RAB9A, BCOR, RPL39, or PNPLA4 was also observed in tumor cell lines." (PMID 25653311, 2015). "In view of the limited evidence on therapies for this extremely rare tumor that matched the methylation class of CNS tumors with BCOR/BCORL1 fusion without a detectable fusion, we reasoned that radiation therapy was warranted given the high proliferative activity." (PMID 40724977, 2025). "Epigenetic modifiers such as KMT2D, BCOR, METTL3 and METTL14 were a limiting factor for uncontrolled cell proliferation in 3D spheroids, which may reveal the mechanism of how they function as tumor suppressors in human cancer." (PMID 38853928, 2025).
tumor (continued). "Our findings suggest this rare tumor type may mainly affect adults in intra/juxta-ventricular locations, unlike their counterparts having the BCOR ITD alteration, thus constituting a novel diagnosis for neuropathologists to consider." (PMID 36782314, 2023). "However, PRC upregulation was not highlighted in the original study of CNS tumors with BCOR alterations when they compared expression within four newly described tumor entities." (PMID 33920124, 2021). "EZH2 was highly expressed in CCSKs irrespective of whether the tumour harboured the BCOR-ITD or the YWHAE-NUTM2B/E fusion transcript (not shown)." (PMID 26848979, 2016). "Furthermore, BCOR was found highly expressed in CCSK, suggesting that this gene could represent a key factor in supporting tumor growth, through its interaction with BCL6 and through the altered epigenetic signaling." (PMID 26516930, 2015). "Notably, the BCOR-rearranged tumor showed no expression by immunohistochemistry." (PMID 36690805, 2023). "However, difference between the two tumor groups in terms of overall survival is not as pronounced (median overall survival of 38 months, varying from 2 to 170 months after the initial diagnosis for BCOR ITD)." (PMID 36782314, 2023). "However, they did not observe preferential BCOR staining for specific tumor locations." (PMID 34680383, 2021). "INI-1 was retained in the tumor cells, and WT1, desmin, myogenin, BCOR, TLE-1, CD45CLA, and synaptophysin were all negative (not shown)." (PMID 41230381, 2026). "Using immunohistochemistry, tumor cells presented a preserved expression of INI1, BRG1, and there was no immunopositivity for LIN28A or BCOR." (PMID 37349135, 2023). "Tumor specimens negative for EWS-specific fusion gene should be analyzed for the panel of known fusion transcripts including CIC-rearrangement, BCOR-rearrangement, EWSR1, or FUS fusion with no-ETS partner." (PMID 36358827, 2022). "Further workup showed the tumor to be negative for ETV6 and BCOR gene rearrangement by FISH, and negative for BCOR ITD and NTRK gene rearrangement by NGS." (PMID 32490123, 2020). "Immunostaining revealed that the tumor cells were positive for TLE1 and BCOR, and negative for cytokeratin (AE1/AE3), Desmin, CD45, S100, CD31, HMB45, and SATB2." (PMID 31702654, 2019). "Further, immunostaining of tumor cells was positive for TLE1 and BCOR, and negative for cytokeratin (AE1/AE3), Desmin, CD45, S100, CD31, HMB45, and SATB2." (PMID 31702654, 2019). "Immunohistochemistry showed benign epithelial positivity for cytokeratin and focal malignant stromal positivity for smooth muscle actin and CD10; however, the tumor was negative for CD99, Wilm's tumor protein, SS18-SSX, BCOR, and estrogen/progesterone receptors." (PMID 41681728, 2026). "The tumor diffusely expressed NUTM1, was positive for WT1cter at weak to moderate intensity, and was focally positive for CD99, while it was negative for keratins, EMA, P40, MyoD1, myogenin, NKX2.2, BCOR, and pan-TRK." (PMID 38851744, 2024). "In the IHC study, tumor cells showed positivity for CD99, EMA, vimentin, and TLE1, while they were negative for NKX2.2, WT1, BCOR, PDGFA, cytokeratins, muscle markers (smooth muscle actin, desmin, caldesmon, MyoD1, and myogenin), and melanocytic markers (HMB45, SOX10, and S100)." (PMID 38339014, 2024).
cancer (51 papers, 2014 to 2026). A tumor composed of atypical neoplastic, often pleomorphic cells that invade other tissues. "While there aren't currently any drugs specifically targeting BCOR mutations, researchers are exploring targeted therapies based on the mechanisms through which BCOR mutations drive cancer development." (PMID 41584037, 2026). "BCOR mutations are directly associated with cancer development by altering the protein's RNA recognition through alternative splicing at the pre-mRNA level." (PMID 39877469, 2025). "This approach identified candidate variants in known cancer genes, including in BCOR, NOTCH2, TET2, NF1, EZH2, and JAK1." (PMID 28721364, 2015). "BCOR mutations are present in a number of malignancies; and correlates with poor cancer prognosis." (PMID 33466343, 2021). "Both MLL2 and BCOR are classified into the same GO group, “chromatin modification” (GO:0016568); cases with mutated genes belonging to this category accounted for a total of 38.2% of cancers (13/34 cases)." (PMID 25980440, 2015). "BCOR mutations have already been implicated in some cancers." (PMID 25653311, 2015). "BCOR is a common epigenetic regulator specifically important in cell differentiation and development and its role is significant because its alterations, mutations, fusions, or deletion can lead to abnormal gene expression, contributing to the development of cancers." (PMID 39877469, 2025). "Top expressed cancer-implicated gene targets for each TF converged on notable genes involved in cell signaling (SMAD3, PTPRJ), BCL6 regulation (FBXO11, BCOR), and transcriptional regulation (RUNX1, ERG, CUX1)." (PMID 38116118, 2023). "HIOTs were also found in another two cancer genes BCOR (intron) and NCOR2 (intron) by RGN11155 and RGN11189 respectively." (PMID 35831290, 2022). "Although several cancer genes were hit across multiple F-hiPSC lines, only BCOR was found to demonstrate statistically significant positive selection (q = 3.64 × 10 −8) using dNdScv49." (PMID 35953586, 2022). "BCL6 pharmacological inhibitors that block the interaction between BCL6 and BCoR/NCoR/SMRT exert cytotoxicity toward BCL6-addicted cancer cells." (PMID 36377663, 2022). "While the present study found the overexpression of BCOR in HeLa cancer cells, we were unable to confirm, via Western blot, the level of BCOR expression." (PMID 34961030, 2021). "Mutations were found most frequently in 3 genes, STAT3, BCOR, and MLL2 (which were present in 9, 7, and 6 cancer samples, respectively), whereas there were only 2 cases of JAK3 mutation." (PMID 25980440, 2015). "Other recurrently mutated cancer genes included chromatin modifiers KMT2C (n=2) and BCOR (n=2)." (PMID 38978571, 2024). "In the TCGA cancer genomics dataset, the transcription factors (TFs) BCOR (BCL6 corepressor, FDR = 1.2 × 10–35) and BCLAF1 (Bcl-2-associated transcription factor 1; ActiveDriver FDR = 9.8 × 10–4) were significantly enriched in substitutions in glycosylation sites." (PMID 33834021, 2021). "Cancer Genome Atlas (TCGA) pan-cancer analysis suggested that the association of KMT2C/BCOR/KDM5C mutations with ICB response observed here might not result from DNA repair defects." (PMID 35681795, 2022). "Whether BCOR-altered cancers are dependent on other ncPRC1.1 subunits remains to be determined." (PMID 34617019, 2021). "Other known recurrent cancer genes with ≥10 occurrences include PLEC, PDGFRA, NF1, ARID1A, BCOR, and ACVR1." (PMID 41312385, 2025).
cancer (continued). "We found telomere maintaining genes (TERF2, CTC1, and ACD), genes involved in zinc homeostasis (MTF1 and SLC30A9), transcription elongation factor complex components (ICE1, ICE2, ELL), and BCL6 corepressors (BCOR, BCORL1) uniquely invoked in TNBC cancers." (PMID 40700427, 2025). "A total of 136 nonsilent NSMs were identified in normal samples, with an average of 4.9, and 81 NSMs were identified in BPHs, with an average of 6.3, in the trio cases (p = 0.042), including the COSMIC cancer genes FOXA1, KMT2C, and BCOR." (PMID 38172600, 2024). "BCOR is likely to be a crucial mediator of BCL6 function in these cancers, whereas BCL6 can coordinate the actions of the BCOR polycomb-like complex (BCOR, PCGF1, RING1B, and KDM2B) to potently repress target genes." (PMID 33468080, 2021). "BCL-6 corepressor (BCOR) and mixed lineage leukemia 2 (MLL2) are epigenetic regulators known to have a role in cancer." (PMID 30935402, 2019). "BCOR acts as a corepressor of BCL6, a potent oncogenic protein in cancers of the lymphoid lineage." (PMID 33468080, 2021). "Considering the angiogenic properties of cancer cells and the recently reported pro-sprouting function of Bcl-6 family member BAZF, we further investigated whether endothelial expression of Bcl-6/BCoR was subject to regulation by angiogenic stimuli." (PMID 27880939, 2017). "Moreover, analysis of TCGA pan-cancer transcriptional and mutational data revealed that the association of KMT2C/BCOR/KDM5C mutations with DNA repair pathway score did not well correlate with the association of KMT2C/BCOR/KDM5C mutations with TMB in the same cancer type." (PMID 35681795, 2022).